TNF (tumor necrosis factor)
Diseases named in the same sentence as TNF in open-access papers (continued):
Sharing a sentence is not in itself a finding about the gene and the disease.
tumor (continued). "The increase in tumor-infiltrating T cell activation and function caused by loss of TNFR1 signaling led us to speculate that the T cells were a direct target of TNF." (PMID 39178856, 2024). "Similarly, TNFα secretion was highest in supernatants containing CD137+ CD8+ T cells after co-culture with autologous tumour cells and lowest in CD137−PD-1− CD8+ T cells." (PMID 38986249, 2024). "Immune cell exhaustion in TME is characterized by persistent tumor antigens stimulation, reduced proliferation capacity, enhanced inhibitory receptor expression, and decreased production of effector cytokines such as IL-2, TNFα, or IFN-γ." (PMID 38533507, 2024). "Additionally, it is reported that TNF-α and hypoxia-inducible factor upregulate the expression of integrin and their ligands on tumor endothelial cells to promote metastasis." (PMID 39076974, 2024). "TNFα, was found to be highly expressed in tumor bearing mice." (PMID 39394174, 2024). "Given that TNF-α and IL-1β promoted the expression of OPN in tumor cells, we wondered whether TNF-α and IL-1β promote the expression of OPN in adjacent macrophages." (PMID 39726047, 2024). "Furthermore, both treatments were effective in inhibiting tumor growth in EA and ES by modulating the levels of interleukin (IL)-6 and tumor necrosis factor (TNF)-α, decreasing mast cells numbers and inducing apoptosis." (PMID 39861087, 2024). "In addition, there is preclinical evidence that combined ICB and TNFα blockade results in better anti-tumor responses and overall survival." (PMID 38333710, 2024). "TNF-α, as one of the main inflammatory cytokines, suppresses immune response by promoting the development of immune-suppressive regulatory T cells and myeloid cells in the tumor microenvironment." (PMID 38191571, 2024). "Inhibiting SPP1 + Mac-derived TNF-α and IL-1β suppressed tumor growth both in vivo and in vitro." (PMID 39726047, 2024). "Macrophage activation and TNF induction were responsible for PAP-I anti-tumor activities." (PMID 39850573, 2024). "The combined action of ALB and TNF-α affects tumor progression and improves patient survival." (PMID 37505298, 2024). "Moreover, IL-17A+ CD8+ T cells secrete IL-17A, which, in conjunction with TNF signaling, can induce iCAFs and promote tumor progression." (PMID 38982491, 2024). "Tumor necrosis factor (TNF) influences tumors by promoting metastasis and tumor growth." (PMID 39519758, 2024). "M1 macrophages primarily demonstrate anti-tumor effects through the secretion of cytokines like tumor necrosis factor-α (TNF-α) and interleukin-6 (IL-6), whereas M2 macrophages primarily release anti-inflammatory cytokines such as interleukin-10 (IL-10), which have promoting effects on tumor growth." (PMID 38637848, 2024). "T cells are specific tumor killer cells that can secrete TNF- α Suppress the growth of tumor cells." (PMID 38773226, 2024). "Although these findings differ from our observations, this discrepancy may stem from differences in the activation of pro-death or pro-survival signaling pathways between HT-22 cells and tumor cells under TNF-α/Smac mimetic induction." (PMID 39682718, 2024). "TNF inhibits tumor growth by inducing apoptosis and inhibiting nuclear factor κB (NF-κB) signaling." (PMID 38297164, 2024). "Additionally, Th1-polarized CD4+ cells release cytokines such as interferon-gamma and tumor necrosis factor-alpha, which improve antigen presentation by dendritic cells and enhance tumor cell recognition." (PMID 39769460, 2024). "Additionally, lymphocytes secrete cytokines such as interferon-gamma (IFN-γ and tumor necrosis factor-alpha (TNF-α which enhance the anti-tumor activity of other immune cells." (PMID 39170737, 2024). "In addition, MMP-9 produced by tumor cells drives malignant progression and metastasis and high levels of inflammatory cytokines such as TNF-α, IL-1β, Il-6, and IL-8 present in CM can also significantly increase MMP-9 expression." (PMID 39072314, 2024).
tumor (continued). "In addition, meta‐analysis of the antitumor function of n‐3 PUFA has proved that the n‐3 PUFA administration can inhibit the function of IL‐6 and TNF, which can promote the tumor growth and metastasis." (PMID 38800967, 2024). "Additionally, the selective apoptosis of tumor cells and virus-infected cells induced by TNF-α requires PACS-2." (PMID 38540691, 2024). "Additionally, the Poly (I:C) (50 μg/mL) can suppress tumour development by induction of M1 tumour suppressor macrophages through an independent TNF-α-mediated pathway." (PMID 38698968, 2024). "These effector T cells from PBMCs treated with CD3 and CD28 antibodies could secrete IFN-γ and TNF-α to act as cytotoxic cytokines together with granzyme B and perforin to initiate apoptosis in tumor cells, thereby killing cancer cells." (PMID 38321486, 2024). "Upon activation, they secrete IFN-γ and TNF-α, which inhibit tumor cell growth." (PMID 39748921, 2024). "Finally, γδT cells serves as potent producers of IFN-γ and TNF-α, exerting anti-tumor effects through various mechanisms, including the inhibition of tumor vascular growth." (PMID 38840908, 2024). "In the context of the associations with IL-4, IL-9, and TNF-α, high SIGLEC9 expression may have a suppressive effect on the immune system, helping the tumor evade elimination by immune cells." (PMID 39727942, 2024). "TNF has been demonstrated to have the double-edged sword effect on tumor growth." (PMID 38594751, 2024). "IFN-γ, LPS, and TNF-a activated M1 macrophages exhibit a more straightforward functional domain and are involved in type I inflammation, killing of intracellular pathogens, and tumor resistance." (PMID 39000461, 2024). "NK cells, a member of the innate lymphoid cell (ILC) family, have a significant impact on anti-tumor immunity which presents direct cytolytic activity interacted with target cells, up-regulated expression of TNF and death-inducing ligands, and a capacity to secrete multiple cytokines and chemokines." (PMID 39055918, 2024). "These pathways were also the top five enriched pathways in the R group of the eight internal HGSOC samples: oxidative phosphorylation in the tumor and stromal regions, TNF-α signaling via NF-κ in the tumor region, G2/M checkpoint, E2F target, and MYC target V1 in the stromal region." (PMID 39135097, 2024). "Combining TNF inhibitors with checkpoint blockade therapies may enhance the overall anti-tumor response by addressing both direct tumor signaling and the immune evasion mechanisms employed by tumor cells." (PMID 39682256, 2024). "In vivo experiments confirm that the TNF‐α overexpression group has larger tumor volumes." (PMID 38739004, 2024). "Interestingly, tumor-infiltrating Th1 cells (IFN-γ+ TNF-α+ CD4+ T cells) were found to be increased in the DT-mediated Foxp3+ Treg-ablated group in comparison to the control." (PMID 39247196, 2024). "Although the role of PGD2 and related ligands requires further attention, remodeling of the tumor immune microenvironment by TNF-α and NF-κB regulating, particularly by reducing the inflammatory cell infiltration, is an intriguing mechanism for resistance to some new immunotherapies." (PMID 38704736, 2024). "This early TNFα effect mediated by the tumor microenvironment has also been shown for STING agonists in the absence of radiation treatment, indicating the importance of understanding how STING agonists affect normal tissue in order to optimize clinical implementation." (PMID 38659582, 2024). "Additionally, the dendritic cell-like biomimetic nanoparticles enhanced IFN-γ and TNF-α expression by naive T lymphocytes and exhibited superior therapeutic outcomes in reducing tumor growth." (PMID 39684867, 2024). "Additionally, the upregulation of genes associated with TNF, IL‐17, and NOD pathways suggests potential alterations in anti‐tumor immune responses." (PMID 38460162, 2024).
tumor (continued). "Activated B cells are known to secrete inflammatory cytokines such as IL-6, Il-1α, TNF-α and Il-1β itself, which may stimulate IL-β secretion and NfκB activation in tumor cells." (PMID 39801513, 2024). "Additionally, the pro-inflammatory cytokine TNFα acts as an inflammatory mediator to trigger EMT of tumor cells and promote metastasis." (PMID 38589501, 2024). "Activated NK cells in the “missing-self recognition” response induce tumor cell death via two major pathways, the release of perforin/granzyme-containing granules and/or death receptor-mediated apoptosis by tumor necrosis factor (TNF) family ligands." (PMID 38635551, 2024). "NGR–hTNF consists of TNF-α linked to peptides containing NGR, which can specifically recognize tumor neovascularization with high CD13 expression and thus deliver high concentrations of TNF-α to exert therapeutic effects on tumor tissues." (PMID 38429828, 2024). "Moreover, inflammatory cytokines IFNγ and TNFα, which are elevated in the serum of tumor-bearing mice, can strikingly stimulate MSCs to produce more G-CSF." (PMID 38690266, 2024). "With Len treatment, tumor microenvironment interactions supported by the transfer of inflammatory cytokines becomes invalid by the modulation of cytokine levels in the microenvironment, represented by the reduction of TNF‐α level." (PMID 39031503, 2024). "We discuss the role of TNF-α in promoting tumor cell vascular adhesion and supporting angiogenesis." (PMID 39927118, 2024). "TNFα and TGFβ mimic only part of the signals emanating from the tumor microenvironment." (PMID 38519642, 2024). "TNF-α participates in inflammatory signaling pathways and contributes to malignant tumor growth." (PMID 38398617, 2024). "TNF‐α can induce tumor cell necroptosis while the direct intravenous administration may lead to systemic toxicity." (PMID 37984863, 2024). "Additionally, vitamin D can downregulate the expression of genes that promote inflammation and tumor growth, including pro-inflammatory cytokines like interleukin-6 (IL-6) and tumor necrosis factor-alpha (TNF-alpha)." (PMID 38927564, 2024). "Deeply analyzing the specific function of TNF signaling pathway in tumor microenvironment may help us to further improve our chemoimmunotherapy hydrogel treatment." (PMID 38594751, 2024). "Genes that we found highly expressed in ever uninfected non-tumor individuals (i.e., 16 upregulated genes) were enriched in functions/pathways such as tumor necrosis factor (TNF) signaling pathway, cytokine-cytokine receptor interaction, hematopoietic cell lineage, and apoptosis." (PMID 38752789, 2024). "Additionally, CD8+ CTLs can secrete cytokines such as TNF, which indirectly contribute to tumor cell death." (PMID 38887597, 2024). "Tumor-associated DCs (TADCs) can release several growth factors and other molecules, including TGF-β, granulocyte-macrophage colony-stimulating factor (GM-CSF), CXCL12, and TNFα, which are all proangiogenic factors." (PMID 39404428, 2024). "The tumor mass comprises several types of cells, such as tumor cells, macrophages, neutrophils, T-lymphocytes, fibroblasts, and endothelial cells that secrete a variety of mediators, including inflammatory cytokines such as TNF-α, IL-1, and IL-6." (PMID 38940936, 2024). "Furthermore, T cells can release cytokines such as interferon-gamma (IFNy) and tumor necrosis factor-alpha (TNFα), which have anti-tumor effects by inducing permanent growth arrest, leading to their elimination and promotion of inflammation." (PMID 38881904, 2024). "TAMs participate in tumor growth and metastasis by releasing TNF-α, TGF‐β, IL6, IL10, and VEGF-A." (PMID 39845973, 2024). "In addition, we also found that CD4+ and CD8+ T cells secreted PD-1, granzyme B, CD107a and TNF-α levels in tumor tissues of KC;Ubr7–/– mice were significantly reduced." (PMID 39424627, 2024). "TNF-α plays a dual role in regulating anti-tumor immune responses." (PMID 38891056, 2024).
tumor (continued). "Finally, we found that neutrophil populations shifted toward IFN-responsive and TNFα-expressing populations in tumors, and that neutrophils in the bone marrow, even in tumor-free mice, had more mature phenotypes in response to EZH2i." (PMID 38265267, 2024). "The reduction in TNFα secretion observed in our experiments upon miR-29 expression further indicates that miR-29a, miR-29b, and miR-29c may inhibit tumor growth, at least in part, by downregulating TNFα." (PMID 38890285, 2024). "In any of the cases, the survival difference is minimal because both subtypes can coexist in the same tumor, and dynamic transitions from a proneural to a mesenchymal phenotype can be induced by TNF-α, temozolomide (TMZ), or radiation through an NF-κB-dependent mechanism." (PMID 38473776, 2024). "Related proinflammatory cytokines, such as tumor necrosis factor alpha (TNF‐α), interleukins and interferons released by tumor cells and various inflammatory cells (neutrophils, dendritic cells, macrophages, lymphocytes, etc.), are involved in local and systemic inflammation of tumors." (PMID 38553949, 2024). "Moreover, Tf-CT-MEs also reduced the serum concentrations of inflammatory factors (TGF-β1, CCL2, TNF-α, and IL-6), and Tf-CT-MEs enhanced tumor targeting, promoted the deep penetration of drug components, and improved the treatment of cervical cancer." (PMID 38957318, 2024). "In addition, the tumor-driven cytokines IL-1, IL-6, and TNF-a suppress natural anticoagulants such as protein C and thrombomodulin, further exacerbating the coagulopathic state in brain cancer." (PMID 39766214, 2024). "VGX-1027, a compound that targets macrophages to reduce the production of TNF-α and IL-1β, was also used to verify whether SPP1 + Mac-derived TNF-α and IL-1β act on tumor cells." (PMID 39726047, 2024). "Consequently, the induction of IFN-γ, TNF-α, and IL-2 in tumor-infiltrating CD8+ T cells by LNP-pE285K-dIgA was inhibited upon Pigr knockdown." (PMID 38886748, 2024). "Scholars have stated that kefir reduces tumor cell viability and growth rates, regulates cytokine expression in tumor tissues (e.g., downregulates IL-6, IL-10 and IL-1β, upregulates TNF-α, IL-10, and IL-4), promotes apoptosis, and exerts immune-enhancing effects." (PMID 39605907, 2024). "It was suggested that inosine might have inhibited tumor invasion and malignant progression by suppressing the overexpression of TNF-α and IL-1β secreted by M1 macrophages, which in turn inhibited tumor invasion and malignant progression." (PMID 39795180, 2024). "Subsequently, the ELISA results of the tumor tissue demonstrated that the higher levels of TNF-α and IL-6 in hNVs, hNVs-EGCG and hNVs@Flu-EGCG groups and lower levels of IL-10 in hNVs, hNVs-EGCG and hNVs@Flu-EGCG groups compared to PBS and PLGA-Flu groups, showed the same result as before." (PMID 38637848, 2024). "In addition to directly targeting tumor cell elimination, CTLs can also release TNF-α into the TME, inducing apoptosis in cancer cells." (PMID 39845973, 2024). "The anti-tumor effects of cannabidiol target mitochondria, inducing a significant increase in ROS production and a reduction in anti-inflammatory responses as reflected by a significant decrease in Tumor Necrosis Factor α (TNF-α) expression levels." (PMID 38543308, 2024). "When TNF-α is at a normal level, it possesses anti-tumor function." (PMID 38996725, 2024). "First, factors such as Interleukin-17A (IL-17A), granulocyte–macrophage colony-stimulating factor (GM-CSF), granulocyte colony-stimulating factor (G-CSF) and tumor necrosis factor-alpha (TNF-α) from the tumor site enter the blood and then stimulate bone marrow production." (PMID 38609997, 2024). "Similarly, cytokines such as TNF-α, interleukin-1 (IL-1), and interferons can regulate tumor apoptosis." (PMID 38612357, 2024).
tumor (continued). "On the other hand, TNF-α suppresses tumor growth through its anti-proliferative, cytostatic, and cytolytic effects against various malignant cells; however, many of these cells are resistant to TNF-α-induced cytotoxicity." (PMID 39408920, 2024). "An increased NLR has the potential to induce neutrophilia owing to the presence of tumor granulocyte colony-stimulating factor, which in turn can expedite tumor progression and augment the concentration of cytokines in the plasma, such as interleukin-6 and tumor necrosis factor-α." (PMID 38623101, 2024). "Simultaneous stimulation of IFN-β and TNF-α signaling induces significant necrosis of tumor cells." (PMID 38817608, 2024). "However, the presence of pro-inflammatory cytokines such ad IL-17, IL-6, IL-1β, and TNF-α leads to the chronic activation of inflammatory signals that not only suppresses adaptive immune responses, but also induce tumor growth." (PMID 39767682, 2024). "V9 treatment also reduced the production of IL-6 but not TNFα in tumor-associated macrophages compared to PBS-treated mice." (PMID 39054536, 2024). "Furthermore, activated CD8+ T cells secrete IFN-γ and TNF-α, initiating a cascade of inhibitory immune responses against the tumor." (PMID 38352877, 2024). "Furthermore, the infiltrating TC had a higher expression of transcripts involved in TNF signaling compared to tumor-adjacent T cells in tumor-sparse regions, indicating that they are activated." (PMID 39001353, 2024). "The TNFα-mediated Fas overexpression is inconsistent with the standard view in which the suppression of NF-κB is considered a potential approach for cancer treatment, as several studies reported tumour-promoting potency of NF-κB." (PMID 38698968, 2024). "But TNF was reported to be cytotoxic to tumour cells and destroy tumour blood vessels." (PMID 38874510, 2024). "Notably, BAY-876 also decreased TNFα-induced IL-8 production, indicating an additional mechanism of possible tumor-suppressive effects." (PMID 39060287, 2024). "Additionally, TNFα has also been shown to mediate the overexpression of MMPs, enhancing the migration of cancer cells and tumor expansion." (PMID 39201656, 2024). "Moreover, NK cells can secrete cytokines, incorporating IFN-γ and TNF-α, which inhibit tumor growth." (PMID 39507529, 2024). "Moreover, the results obtained from in vitro studies on different cell lines show that TNF-α is an essential player in the regulation and activation of NF-κB in tumor cells, where TAMs are one of the sources of these cytokines in the ovarian TME." (PMID 39003350, 2024). "TNF’s role in tumor immunology is akin to a double-edged sword." (PMID 39204319, 2024). "Third, inhibition of TNF-α signaling might reduce the invasiveness of tumor cells, attenuate the ability of neutrophils to bind to tumors as well as to endothelial cells, and limit the extravasation of CTCs." (PMID 39001366, 2024). "Moreover, miR-28 and miR-138 can target immune checkpoints and revert exhausted phenotypes, with miR-28 specifically resulting in interleukin-2 (IL-2) and tumor necrosis factor-alpha (TNF-α) secretion in the tumor microenvironment." (PMID 39329777, 2024). "Additionally, KLK6 plays a role in the tumor microenvironment by stimulating production of tumor necrosis factor alpha (TNF-α) through the activation of protease-activated receptor 1 (PAR-1)." (PMID 39594797, 2024). "Another hypothesis is that the ABO gene is directly related to the level of circulating inflammatory mediators (e.g., TNF-α, E-selectin, or P-selectin) that play a role in the local inflammatory tumor environment." (PMID 39320512, 2024). "They inhibit tumor growth by secreting cytokines, like interferons and tumor necrosis factor." (PMID 39605884, 2024).